XYLB (xylulokinase)
Description:
Phosphorylates D-xylulose to produce D-xylulose 5-phosphate, a molecule that may play an important role in the regulation of glucose metabolism and lipogenesis.
Synonyms: FLJ10343; FLJ12539
Tractability: Small molecule: a structure with a bound ligand is known. PROTAC: ubiquitination databases record sites on it.
Gene: Protein-coding gene on chromosome 3 (38,346,760 to 38,421,348, forward strand). Ensembl gene ENSG00000093217.
Subcellular location (Human Protein Atlas): Nuclear speckles
Pathways (Reactome):
Metabolism: Formation of xylulose-5-phosphate
Gene Ontology:
Molecular function: D-xylulokinase activity; kinase activity
Biological process: xylulose metabolic process; carbohydrate metabolic process; D-glucuronate catabolic process; generation of precursor metabolites and energy; xylulose catabolic process; D-xylose metabolic process
Cellular component: cytosol
Genetic constraint (gnomAD): Loss-of-function variants: 64 observed, 74.7 expected, observed/expected ratio (o/e) 0.86, 90% interval 0.7 to 1.05. The upper end of that interval is the gene's LOEUF score, 1.05, which puts it in group 4 of 6, group 1 being the genes least tolerant of losing a copy. Missense variants: 654 observed, 658 expected, observed/expected ratio (o/e) 0.99, 90% interval 0.93 to 1.06. Synonymous variants: 234 observed, 242.23 expected, observed/expected ratio (o/e) 0.97, 90% interval 0.87 to 1.08.
Homologues: Orthologues: chimpanzee XYLB (99% identical), macaque XYLB (94% identical), dog XYLB (92% identical), pig XYLB (90% identical), rat Xylb (88% identical), mouse Xylb (88% identical), guinea pig XYLB (81% identical), rabbit XYLB (69% identical), tropical clawed frog xylb (64% identical), zebrafish xylb (59% identical), Drosophila melanogaster CG3534 (45% identical), Drosophila melanogaster CG3544 (41% identical), and 1 more. Paralogues in human: GK2 (16% identical), GK (15% identical), GK5 (15% identical), GK3 (15% identical), FGGY (15% identical), SHPK (12% identical).
Diseases named in the same sentence as XYLB in open-access papers:
XYLB is named in the same sentence as 13 diseases in open-access papers, as found by Europe PMC text mining. Sharing a sentence is not in itself a finding about the gene and the disease. The quoted sentences say what the papers report.
COVID-19 (1 paper, 2021). A disease caused by infection with severe acute respiratory syndrome coronavirus 2. "Additionally, S1A-domain represses xylulokinase XYLB, and decreasing of its product (Xu5P) was proposed as one of the potential metabolomics biomarkers of COVID-19." (PMID 34659373, 2021).
glioma (1 paper, 2021). A benign or malignant brain and spinal cord tumor that arises from glial cells (astrocytes, oligodendrocytes, ependymal cells). "The present study was novel in building a uronic acid metabolic process–related signature involving five genes (UGT8, DCXR, SORD, XYLB, and CRYL1) to predict the survival of glioma in the CGGA database." (PMID 33324981, 2021).
ischemic stroke (1 paper, 2020). A stroke disorder caused by obstruction of blood flow to the brain, due to thrombotic (local blood clot formation) or embolic (due to a blood clot or other material traveling from another site) event. "XYLB (p = 6.72E-05, rs196376) had been reported to be associated with neurological diseases such as ischemic stroke." (PMID 33372590, 2020).
prostate carcinoma (1 paper, 2025). A carcinoma that arises from epithelial cells of the prostate gland. "Furthermore, the gene XYLB is involved in carbohydrate metabolism, might affect cancer metabolism, supporting the rapid growth characteristic of cancer cells, although its direct links to prostate cancer are less established." (PMID 40104216, 2025).
tumor (1 paper, 2025). "Exome sequencing identified unique variants in AA patient samples within key genes, including TP73 (tumor suppression), XYLB (metabolism), ALDH4A1 (oxidative stress), PTPRB (cellular signaling), and HLA-DRB5 (immune response)." (PMID 40104216, 2025).
XYLB also shares sentences with these, for which no sentence is quoted: Alzheimer disease (1 paper); cancer (1); Hypertension (1); legionellosis (1); metabolic disease (1); neurological diseases (1); pertussis (1); schizophrenia (1).